CCND2 (cyclin D2)
Diseases named in the same sentence as CCND2 in open-access papers (continued):
Sharing a sentence is not in itself a finding about the gene and the disease.
tumor (continued). "Downregulation of CCND2, a protein known to cause growth arrest in the G1 cell cycle phase, and CD81, a protein relevant for membrane organization, protein trafficking, cellular fusion and cell-cell interactions, contributes to a decreased proliferation, tumor progression, migration, and invasion." (PMID 33690729, 2021). "Even some studies showed that CCND2 methylation could promote tumor progression." (PMID 34545634, 2021). "Binding of Stat3 to the cyclin D2 (CCND2) promoter increases the transcription of CCND2 to maintain a complete cell cycle and allow for low‐level DNA damage accumulation, thereby inhibiting apoptosis, enhancing clonal formation, and promoting tumor radioresistance." (PMID 34766149, 2021). "An attempt was made to create a panel of markers, including two genes (C-MYC and CCND2) common to both the pathways, along with other correlated genes, which was evaluated in a larger cohort of either condition for their usefulness in the detection of neoplasia in both CRC conditions." (PMID 27080994, 2016). "Thus, the expression analysis data lead us to the prediction of new axis that c-Myc might repress the tumor suppressive miRNAs, let-7a, miR-16 and miR-29b, and the inhibition of these miRNAs might result in the up-regulation of CCND2 in ES cells." (PMID 26393798, 2015). "Interestingly, the methylation of the promoter in primary tumor samples was associated with low or no expression of Cyclin D2." (PMID 21059263, 2010). "In contrast to cyclin D1 protein, whose overexpression was distributed equally between the different TNM tumour stages, our data show a trend (P=0.1, 90% significance) that may point towards a positive relation between overexpression of cyclin D2 protein and higher TNM stage of the tumour." (PMID 16012517, 2005). "Furthermore, the data suggest that cyclin D2 protein overexpression may be related to a higher stage of the tumour." (PMID 16012517, 2005). "Alternatively, a tumour may exhibit heterogeneity in cyclin D2 methylation." (PMID 12771922, 2003). "ZKSCAN3 plays an important role in tumor progression by regulating key molecules such as VEGF, ITGβ4, MMP2, MMP9, CCND1, and CCND2." (PMID 40723888, 2025). "The microRNA, miR-1297, targets CCND2 directly, resulting in proliferation inhibition, G1 phase arrest and reduced tumour growth in OSA, and miR-2682-3p also targets CCND2 in OSA." (PMID 40566602, 2025). "In our case, the tumor specimen presented heterozygous deletions of CDKN2A, CDKN2B and CDKN2C, and gains of CDK6 and CCND2." (PMID 38369555, 2024). "This increase in cyclin D2 in LS 174T CRC cells is required to confer the tumorigenic and metastatic properties during L1-mediated tumor development." (PMID 39513917, 2024). "In a miR-1-induced manner, silencing of HOTAIR markedly decreased the tumour growth in vivo as well as the growth of FTC-133 and TPC-1 cell lines via controlling the expression of CCND2." (PMID 39558949, 2024). "For example, TAGLN2, CCND2, and CCL8 were identified in the study and were previously well-established as tumor suppressor genes." (PMID 38234400, 2023). "FBXL8 knockdown leads to the accumulation of CCND2 and IRF5 in breast cancer cells and inhibited tumour progression." (PMID 36855778, 2023). "Despite the inability to precisely assess the differences between normal lung tissue and malignancies, the preliminary findings suggest increased expression of CCND2 and PDGFB in tumor tissues." (PMID 36816016, 2023). "Transcript levels of β-catenin target proteins such as Ccnd2, CDKN2A, and BIRC5 are known to be increased in tumor patients." (PMID 36209344, 2022). "The remaining six genes (e.g., PPP3CC, ITGA5, ITK, CDC25B, CCND2, and THY1) were expressed at higher levels in CD45+ TAS as compared to CD45+ tumor." (PMID 36230846, 2022).
tumor (continued). "Some of the RNAs that encode the proteins regulating the cell cycle were increased (such as p21) or decreased (such as cyclin D2) in TRIM28 KO cell clones; a tumor marker, the MAGE (melanoma antigen) family, which is involved in cell proliferation was reduced." (PMID 35743282, 2022). "Most notably, we found that CCND1 and CCND2 were significantly downregulated upon PAIP1 knockdown in SMMC-7721 xenograft tumor cells, suggesting that PAIP1 promotes CCND1, CCND2, and MDM2 expression in HCC cells." (PMID 36436074, 2022). "CCND2 is 1 of the significantly downregulated genes, and the decrease of CCND2 was confirmed by qPCR in SURC knockdown CRC cells and s.c. tumor tissues." (PMID 35617032, 2022). "Key regulators of cell-cycle progression and inflammation, including Cyclin D1, Cyclin D2, COX-2 were shown to be favorably modulated by Anthos, with the most dramatic reductions in expression observed in tumor tissue samples." (PMID 34926717, 2021). "FBXL8 was found to interact with two tumor-suppressors, CCND2 (cyclin D2) and IRF5 (interferon regulatory factor 5)." (PMID 32784654, 2020). "For this analysis, groups of BALB/c nude mice (n = 10) were subcutaneously injected with HeLa cells transfected with the CCND2 AS1 overexpression plasmid or a control plasmid, and tumor growth was monitored." (PMID 32607313, 2020). "Stratification according to HPV status revealed that both HPV(+) and HPV(−) tumors displayed significant upregulation of CCND2, while downregulation of CCND2 was observed only in a few HPV(−) tumors and a single HPV(+) tumor." (PMID 32224897, 2020). "It has emerged that cyclin D2, MMP-9, and miR-204 expression are inversely correlated and that miR-204 targets cyclin D2 and MMP-9, inhibiting tumor growth in Rb." (PMID 31798638, 2019). "These pathways were all connected to tumor growth, and the PI3K/Akt signaling pathway (eight involved genes: CCND2, CDKN1B, CSF1, EFNA3, FGFR2, FGFR3, IL2RB, and ITGA9) ranked first among upregulated pathways (Enrichment Score = 3.159187)." (PMID 30755239, 2019). "The tumor had a highly rearranged genome with high-level focal amplifications of MYCN (319 CN; 660 FPKM), CCND2 (123 CN; FPKM 2516) and GLI2 (11 CN; FPKM 24)." (PMID 30262806, 2018). "Systemically delivered agomiR-4317 reduced tumor growth and inhibited FGF9 and CCND2 protein expression." (PMID 30227870, 2018). "The mRNA expression of oncogenic proteins STAT3, IGF1, cyclin D2, and c-MYC increased with respect to increasing glucose concentrations while FOXO1 (tumor suppressor) showed decreased mRNA expression." (PMID 28114390, 2017). "We observed substantially improved survival with high lifetime prediagnostic RPA in women with a tumor-methylated APC, CCND2, HIN1, or TWIST1 gene promoter compared with active women with unmethylated gene promoters." (PMID 28222775, 2017). "Among these genes, many are involved in tumour suppression [e.g. RB1], apoptosis [e.g. BCL2L1], the cell cycle [e.g. CCND1, CCND2] or protein kinases [e.g. KIT, GSK3‐β]." (PMID 28539478, 2017). "Collected the tumor tissues were subjected to western blot showed decreased protein expression of pSTAT3 ser727, total STAT3, Bcl-2, Bcl-XL, FAS, cyclin D2, MMP2, and MMP9 in metformin treated vs. control mice." (PMID 28114390, 2017). "Role of microRNA-182 in posterior uveal melanoma: regulation of tumor development through MITF, BCL2 and cyclin D2." (PMID 32309578, 2016). "In conclusion, our results demonstrated that miR- 146a-5p acted as a tumor suppressor through directly targeting CCND1 and CCND2 in the NSCLC cell lines, H1299 and SPCA-1." (PMID 27494902, 2016).
tumor (continued). "CCND2 has also been reported to be the only one of D-type cyclins, being up-regulated in the conditions of growth arrest, ectopic expression of CCND2 blocked the progression of cell cycle, suggesting that CCND2 might function as a tumor suppressor gene in a cancer-type dependent manner." (PMID 27583477, 2016). "The qRT-PCR based panel of MYC, MYCN, CCND1, CCND2, EGFR and FNDC3A was successful in detecting neoplasia with an overall accuracy of 54 % in S-CRN compared to that of 29 % in UC neoplastic samples." (PMID 27080994, 2016). "In only 59 % (10/17), 53 % (9/17), 41 % (7/17), 38 % (6/16) and 35 % (6/17) of the tumor samples, RASSF1A, HIN-1, MGMT, DAPK1 and CCND2 promoters showed methylation status ≥ LOQ." (PMID 26370119, 2015). "c-Myc exhibited inverse correlation with let-7a, miR-16 and miR-29b, and these tumor suppressive miRNAs played important roles in SKES1 proliferation and tumorigenesis by targeting CCND2 both in vitro and ex vivo treatment." (PMID 26393798, 2015). "Their loss, by releasing the inhibition upon tumor-promoting genes, such as BCL2, BMI1, CCND2 and CCND1, promotes cell growth and tumor progression." (PMID 24566314, 2014). "Other examples include MCM10 and CCND1 also targeted by miR-199a-5p, PBK, that promotes tumour cell proliferation through p38 MAPK activity that is targeted by miR-28-5p and cyclin genes CCND1 and CCND2 targeted by miR-150." (PMID 25200074, 2014). "Mechanistically, the effects of miR-191 and miR-425 on tumor growth and invasion require, at least in part, the suppression of SATB1, CCND2 and FSCN1." (PMID 23505378, 2013). "In total, our data uncovered important roles for CCND2, HOXC6 and PLXNA1 in regulating ERMS proliferation, validating the role of several novel genes in regulating continued tumor cell proliferation in human ERMS cells." (PMID 24009521, 2013). "However, cyclin D2 and α-inhibin double-knockout mice lived longer than mice lacking α-inhibin alone, suggesting that p27Kip1 acts cooperatively with inhibins to negatively regulate granulosa cell proliferation and cyclin D2 may antagonize the tumor-suppressing actions of p27Kip1." (PMID 23155381, 2012). "The down-regulation of cyclin D2 in INV cells suggests neosis, an important process that mediates tumor cell resistance to apoptosis, heterogeneity and continuity." (PMID 21858074, 2011). "We also assessed the methylation status of the Cyclin D2 and PTCH1 promoters in these 14 cell lines and 58 primary tumor samples." (PMID 21059263, 2010). "BCL2, MYC, CCND2, BCL6 and LMO2 expression was studied in tumor tissue from 12 DLBCL patients of our series using real-time PCR." (PMID 20016842, 2009). "This is most likely due to increased cellular proliferation in tumor cells, as E2F is important in cell proliferation control and MYC is both a p21-repressor and inducer of cyclin D2 and cyclin-dependent kinase binding protein CksHs2." (PMID 19798449, 2009). "For RASSF1A, CCND2, GSTP1, TWIST, and APC genes, the proportion of methylated genes was significantly higher in the ER-positive than in the ER-negative tumor group." (PMID 18485221, 2008). "In early stages of tumor progression (T1 and N0), RASSF1A and CCND2 were significantly (P < 0.05) more methylated in ER-positive than in ER-negative tumors." (PMID 18485221, 2008). "The frequency of promoter hypermethylation of the tumor suppressor gene loci included in the panel was FHIT 28%, FANCF 24%, Cyclin-D2 12%, BRCA2 4%, and RUNX3 56% of the 25 tumours." (PMID 15574200, 2004).
tumor (continued). "In addition, a previous study reported that BAP18 is upregulated in NSCLC tissues and promotes tumor cell proliferation by transcriptionally activating CCND1 and CCND2, suggesting a potential oncogenic role." (PMID 40818609, 2025). "Cord blood from newborns (WBCs) DNA methylation of the ACSL3 promoter, Intragenic p19INK4α DNA methylation in adult blood (PBLs), CDH1, HIN1, PARPβ, and TWIST promoter DNA methylation in adult tumor tissue DNA methylation of the ESR1 promoter, BRCA1, CCND2, and DAPK." (PMID 40182693, 2025). "Notably, several genes involved in cell cycle regulation (CCND2, CDKN2A/C), tumor microenvironment (COL3A1, COL1A1), and growth factor signaling (FGF18, ERBB2) showed significant upregulation with fold changes ranging from 1.5 to 2.0." (PMID 41419500, 2025). "Accordingly, immunostaining in 41 tumor and unaffected adjacent tissues showed reduced levels of JUN; downregulation at the transcript level was also observed for JUN, FOS (Fos proto-oncogene, AP-1 transcription factor subunit), and CCND2." (PMID 39199659, 2024). "Similarly, after their culture with ECs, IL30-overexpressing PCs showed a dramatic upregulation of a wide range of oncogenes, which included CCND2, EGR3, IGFBP5, KLK3, PDLIM4, PTGS1 and SHBG and a few tumor suppressors, such as GPX3, FOXO1, MAX and NKX3-1." (PMID 38087324, 2023). "Indeed, gene set enrichment and leading-edge analyses of activated, (shared) tissue, inflammatory and tumor-infiltrating Treg cell gene sets amongst others revealed sharing of the core eTreg cell genes, including BATF, CCND2, CCR8, TNFRSF18, and VDR." (PMID 33976194, 2021). "Naïve MSCs can inhibit Wnt signalling pathways through modulating the Dickkopf-related protein 1 (DKK1) released by tumor cells, and subsequently downregulating c-Myc and Cyclin D2 and upregulated expression of P21CIP1 and P27KIP1, leading to tumor cells suppression." (PMID 33685452, 2021). "Staining of the CAM tumor with human cyclin D2 antibody detected a strong signal compared to the negative control." (PMID 34685592, 2021). "Collectively, these results demonstrate that miR‐646 acts as a tumor suppressor in NSCLC by targeting FGF2 and CCND2, and may serve as a therapeutic target for patients with NSCLC." (PMID 32347652, 2020). "To explore whether miR-124 played the tumor suppressive roles in SW1783 and U373 cells by targeting CCND2, we re-expressed CCND2 expression in SW1783 and U373 cells." (PMID 33005182, 2020). "However, compared with the control animals, mice overexpressing CCND2 AS1 exhibited significantly reduced tumor growth, as reflected by the tumor weights and volumes." (PMID 32607313, 2020). "We further validated two of the in silico predicted binding partners, CCND2 and IRF5 (tumor-suppressors), and empirically demonstrated their functional roles which might countermeasure FBXL8, in cancer cells." (PMID 32784654, 2020). "As HIF-1α induces the expression of genes related with tumor survival, we assessed the mRNA levels of CCND2, VEGF, BNIP3L, and CA9, and found that CCND2, VEGF, BNIP3L, and CA9 were upregulated when spheroids were treated with OA, whereas their mRNA levels decreased upon FABP5 or HIF-1α silencing." (PMID 33128030, 2020). "Due to limited numbers of included studies, correlation between CCND2 and OS in other ethnicities or tumor types have not been further analyzed." (PMID 30950241, 2019). "When the log rank p value was obtained for cyclin D2 low vs. high expressers, it was statistically significant in LUAD, PAAD, BRCA, and GBM (Fig. 7B1–4), but not in ESCA (Fig. 7B5), and a low hazard ratio (<1) was observed in all tumor types." (PMID 31527584, 2019).
tumor (continued). "The Multiple Beam Search (MBS) algorithm learned interactions from data and discovered that hsa-miR-21, hsa-miR-10b, hsa-miR-448, and hsa-miR-96 interact with oncogenes, such as, CCND2, ESR1, MET, NOTCH1, TGFBR2 and TGFB1 that promote tumor metastasis, invasion, and cell proliferation." (PMID 28793339, 2017). "Sixteen primary matched tumor and serum were analyzed by quantitative methylation specific PCR (QMSP) to determine analytical and clinical sensitivity of the genes tested (SSBP2, MCAM, ERα, ERβ, APC, CCND2, MGMT, GSTP1, p16 and RARβ2)." (PMID 28147335, 2017). "Previous studies have suggested that ZKSCAN3 directly or indirectly regulates the expression of various genes, such as CCND1, CCND2, EGFR, IGF-2, integrin-β4, NF-κB, and VEGF, all of which are known to involve tumorigenesis, tumor progression, and/or metastasis." (PMID 27447553, 2016). "We next determined whether the inhibition of CCND2 and CCND3 was responsible for the inhibition of tumor cell proliferation and invasion observed upon miR-503 modulation." (PMID 25860935, 2015). "Moreover, SATB1 and CCND2 repression by miR-191 are related to the suppression of the PI3K/AKT pathway and the corresponding reduced cell proliferation and tumor growth." (PMID 23505378, 2013). "The immunostained tissue samples revealed that both the tumor cells and duct epithelial cells of the adjacent benign pancreatic tissues did not express cyclin D2." (PMID 24116110, 2013). "Most importantly, tumour growth and development in ApcMin/+ mice was strongly perturbed in mice lacking cyclin D2." (PMID 21288356, 2011). "Most of the primary tumor samples showed high expression levels of the GLI1 protein but these samples did not express Cyclin D2." (PMID 21059263, 2010). "In methylated tumours and in normal gastric tissues, there was no cyclin D2 immunoreactivity detected." (PMID 12771922, 2003). "In contrast, the two tumours with strong cyclin D2 expression (T2, T39) had virtually no methylation detected." (PMID 12771922, 2003). "In addition, CCND2 and MDM2 were among the most amplified genes in the cohort, both involved in the transition to the S phase of the cell cycle, suggesting the importance of this pathway in ALM pathogenesis and tumor evolution." (PMID 40362334, 2025). "This study thoroughly evaluated the high methylation status of the CCND2 promoter region in UCEC tissues and the significantly reduced mRNA expression level, which was considered an early event in tumor occurrence and may serve as a potential biomarker for early diagnosis of UCEC." (PMID 40678058, 2025). "The hypermethylation of the CCND2 promoter region in UCEC tissues is negatively correlated with low mRNA expression, indicating that high methylation may suppress CCND2 gene expression and participate in tumor occurrence and development." (PMID 40678058, 2025). "Cyclin D2 overexpression without L1 in LS 174T CRC cells could also enhance tumor growth, suggesting that increased cyclin D2 expression is a powerful pro-tumorigenic event that can confer tumor growth in human CRC cells." (PMID 39513917, 2024). "The ultimate expression of the downstream targets cyclin D1, cyclin D2 and COX-2 were also significantly downregulated in the Anthos group for both adjacent normal (P = 0.0009, P = 0.001, and P = 0.0009, respectively) and tumor tissue samples (P = 0.0004, P = 0.03, and P = 0.03, respectively)." (PMID 34926717, 2021). "RT-PCR analysis of the transcriptional expression of cell cycle genes showed a significantly increased expression of ccnA1, ccnB2, ccnD3, ccnE1, cdc25b, and E2F1 and a significantly decreased expression of ccnD2 in the Fhit-transfected versus non-transfected tumor cells." (PMID 32545680, 2020).